IL6 (interleukin 6)
Diseases named in the same sentence as IL6 in open-access papers (continued):
Sharing a sentence is not in itself a finding about the gene and the disease.
COVID-19 (continued). "We investigated serum D-dimers, CRP, ferritin, cardiac troponin I, IL-6 levels during the acute phase of infection (SARS-CoV-2 RNA positive) and were monitored longitudinally in hospitalized patients with moderate to severe COVID-19 and in mild ambulatory COVID-19 patients in home quarantine." (PMID 34262116, 2021). "In the milder stage of COVID-19, a positive correlation was detected between IL-33 and IL-1β, IL-12 and IL-23, while a stronger positive correlation between the serum values of IL-33 and TNF-α, IL-1β, IL-6, and IL-12 and IL-23 was detected in patients with COVID-19 with severe disease." (PMID 34917631, 2021). "Besides IL-6, SARS-CoV-2 infection leads to the secretion of high amounts of IL-1β, IL-2, IL-4, IL-7, IL-10, monocyte chemoattractant protein (MCP)-1, and tumor necrosis factor (TNF)-α into the plasma of COVID-19 patients." (PMID 34122407, 2021). "We also identified 35 drugs targeting ALPL, CXCL8, and IL6 that were not previously tested against COVID-19 symptoms and could be repurposed for anti-SARS-CoV-2 management." (PMID 34582497, 2021). "Interestingly, in the current study IL-6 was significantly higher in COVID-19 patients with AKI compared to IL-6 levels in those without AKI (data not shown)." (PMID 34110585, 2021). "In this study, compared with patients with moderate COVID-19, those severe to critical patients showed elder age, active cellular immunity (lower lymphocyte but higher CD3+CD19−level), and increased inflammatory response [higher neutrophil and interleukin-6 (IL-6) level)] at the baseline." (PMID 35071229, 2021). "A cross-sectional study found a correlation between higher inflammatory markers in the serum of patients with more severe COVID-19, including cytokines such as IL-2R, IL-6, and TNF-a, suggesting that the inflammation level may predict disease severity in COVID-19." (PMID 34367693, 2021). "Interleukin-6 (IL6), a proinflammatory cytokine that enables virus to enter host cells and proliferate, is an important prognostic biomarker and a powerful predictor of COVID-19 mortality; it is significantly increased in ICU patients, and was highly significantly correlated with COVID-19 mortality." (PMID 34975885, 2021). "In addition, in the same experimental setting we found a remarkable production of inflammatory cytokines such as IL-6, TNF-α and IL-1β, which are well-recognized players of the cytokine storm occurring in COVID-19 patients, while IL-12p70 level was unchanged in SARS-CoV-2-stimulated PBMC." (PMID 34473805, 2021). "Furthermore, while not assessed in this study, IL6 shows some evidence of decreasing disease remission in COVID-19 patients and is, therefore, a viable target for treating the cytokine storm during disease progression." (PMID 33737684, 2021). "IL-6 may play a negative role in the course of COVID-19 by inhibiting Th1-dependent immunity and stimulating Th17 lymphocytes, thus leading to an increased probability of a cytokine storm." (PMID 33467724, 2021). "Importantly, IL-6, TNF-α have been reported to predict the severity of COVID-19 patients." (PMID 33763078, 2021). "Furthermore, despite including laboratory data obtained on the same day as the chest CT, we did not provide correlation analysis with biomarkers (e.g., interleukin-6, C-reactive protein, D-dimer, ferritin, etc.)known to be predictors of mortality in COVID-19." (PMID 34419163, 2021). "In agreement with this study, these findings indicated the importance of IL6, TNF and IL1B hub-high traffic genes, considered potential targets (individually or in combination) for development of effective therapeutic immunomodulation strategies to manage COVID-19 hyperinflammation." (PMID 34975885, 2021). "Therefore, IL-6 and IL-6 AMP are biomarkers of hyperactivation of inflammatory machinery exacerbated by ACE2 blocking and viral infection, which represent key cytokines in deciphering cytokine-related syndrome and disease progression of COVID-19." (PMID 33503821, 2021).
COVID-19 (continued). "This study emphasizes that biologically active components of spices might alleviate the sustained pro-inflammatory condition by inhibiting the activity of tumor necrosis factor-alpha (TNF-α), interleukins (IL6, IL8), and chemokine (CCL2) known to be elevated in COVID-19." (PMID 34513735, 2021). "Nevertheless, the levels of inflammatory indicators, including IL-6, C-reactive protein (CRP), and lactate dehydrogenase (LDH) in patients’ plasma, were consistently higher in critical and fatal cases when compared to mild COVID-19 cases throughout the acute phase of infection." (PMID 34367117, 2021). "Severe COVID-19 patients also mostly exerted viral infection-induced hyperinflammatory state, mainly characterized by sustained increases in TNF-α, IL-6, and IL-1 levels, and disrupted monocyte and dendritic cell phenotypes, which could ultimately contribute to poor prognosis and mortality." (PMID 34593760, 2021). "These questions not only center around cytokines thought to be playing a central role in COVID-19, including IL-6 and IL-8, but also multiple other cytokines that were elevated in severe COVID-19 patients from one laboratory vendor but not another in our own experience." (PMID 34358229, 2021). "IL-6 inhibition might ameliorate the vascular damage in patients with severe COVID-19 who did not require MVM." (PMID 34631752, 2021). "The first line of therapy for many inflammatory diseases as well as respiratory infections is Dex, which lowers the expression of pro-inflammatory cytokines including IL-6, and which has been proven effective in COVID-19 patients requiring, invasive or not, oxygenation." (PMID 34576169, 2021). "In line with this, serum levels of pro-inflammatory markers IL-6, C-reactive protein (CRP) and soluble IL2-receptor (sIL-2R) expression were higher and number of cytotoxic CD8+ T cells was lower in patients with severe/critical COVID-19 compared to mild COVID-19 of our study." (PMID 34869058, 2021). "TCs have shown great potential for the management of COVID-19 through inhibition of SARS-CoV-2–induced hyperinflammation and cytokine storm, since TCs downregulate the production of inflammatory cytokines, including interleukins (IL-6, IL-33, and IL-1β) and tumor necrosis factor (TNF)-α." (PMID 33967777, 2021). "Notably, compared to wave 1, only IP-10 concentrations were significantly higher in severe versus mild COVID-19 patients, with no change of IL-1ra and IL-6 levels." (PMID 34675240, 2021). "Pro-inflammatory cytokines such as interleukin-1 (IL-1), IL-6, IL-8, and tumor necrosis factor alpha (TNF-α) have been found to be elevated in the sera of severely and critically ill COVID-19 patients, anti-inflammatory cytokines such as IL-10 have also been found in the sera of COVID-19 patients." (PMID 34335566, 2021). "Serum IL-6 was higher in COVID-19 patients with pneumonia than those without pneumonia." (PMID 35136584, 2021). "This could explain the significantly lower serum concentrations of IL-6 and IL-17 in COVID-19 patients with GI symptoms, ultimately resulting in a lower mortality when compared to COVID-19 patients without GI-symptoms symptoms." (PMID 33608656, 2021). "It is known that cytokine storm in COVID-19 consists of various, not necessarily overlapping, soluble immune mediators (SIMs) including IL-1β, IL-6, IL-8, and tumor necrosis factor-alpha (TNF-α) which could yield different predictive value." (PMID 33918563, 2021). "Additionally, IL-1β, IL-6, and IL-8 were significantly upregulated in the critical COVID-19 non-survival group compared to the survival group." (PMID 34276659, 2021). "Our study suggests that seven indices (T, Th, Tc, IL-6, IL-10, RBC, Hb) are helpful for early diagnosis of COVID-19 severity in children, and may provide a laboratory basis for clinicians to offer timely treatment to children with critical COVID-19." (PMID 33865340, 2021).
COVID-19 (continued). "Notably, elevated IL-6 levels had higher odds of severe COVID-19 among MAFLD patients than non-MAFLD patients." (PMID 33763027, 2021). "PIMS-TS children had significantly elevated levels of cytokines, IFNγ, IL-2, TNFα, IL-1α, IFNα, IFNβ, IL-6, IL-15, IL-17A, GM-CSF, IL-10, IL-33 and IL-Ra; elevated chemokines, CCL2, CCL19, CCL20 and CXCL10 and elevated VEGF, Granzyme B and PDL-1 in comparison to COVID-19, seropositive and controls." (PMID 33813138, 2021). "Patients who are critically ill with COVID-19 are subject to the development of life-threatening acute systemic inflammatory syndromes characterized by multi-organ failure and cytokine-release syndrome (CRS), marked by elevated levels of the proinflammatory cytokine interleukin 6 (IL-6)." (PMID 34177298, 2021). "High cytokine levels, in particular IL-6, have also been described to be responsible for lung damage, inducing vascular endothelial growth factor (VEGF) expression in epithelial cells and increasing vessel permeability in SARS as well as for lethal complications of COVID-19." (PMID 33808471, 2021). "Another study also supported the use of ACEi/ARB in improving clinical outcomes of COVID-19 patients with hypertension, as they found that using ACEi/ARB could significantly reduce the level of interleukin 6 while increasing the level of peripheral blood T cells." (PMID 34136537, 2021). "Based on current knowledge, it would seem that more than one cytokine, chemokine, or infiltrating cell type is involved; however, at present, the interplay among IL-6, CXCL10, and macrophages, could represent a main circuit for the onset maintenance and progression of CS in COVID-19." (PMID 33981314, 2021). "The evidence of massively high levels of a subset of cytokines—such as IL-6 and TNF-α—in critically ill patients has led to the hypothesis that, in the setting of the COVID-19-related cytokine storm, they could have a major role in enhancing the endothelial damage." (PMID 34769454, 2021). "Nineteen studies assessed fatal and non-fatal groups of patients with COVID-19 and reported IL-6." (PMID 34185801, 2021). "NGAL is known to be inflammation-driven, and the lack of NGAL upregulation might be attributed to a lack of renal inflammation since in COVID-19 patients the mRNA levels of renal IL-6, TNFα and MMP8 were similar to controls." (PMID 34112226, 2021). "Similarly, it was reported that a prompt decrease in CRP and IL-6 was found in responders of severely ill patients with COVID-19 to tocilizumab but not in non-responders." (PMID 34631752, 2021). "TH17 cells have a major role in inducing the proinflammatory effects of cytokines (G-CSF, IL1B, IL6, and TNF) and chemokines (KC, MIP2A, IL8, IP10, MIP3A) through secretion of inerleukin-17 (IL17), thus contributing to the cytokine storm and subsequent ARDS in COVID-19 patients." (PMID 34975885, 2021). "In fact, in critically ill COVID-19 patients, IFN-I and INF-III levels and IFN-stimulated gene responses are lower compared with other respiratory viruses, while proinflammatory cytokines, including interleukin-2 (IL-2), IL-6, and tumor necrosis factor (TNF), are increased." (PMID 34769508, 2021). "Additionally, in non-severe COVID-19—although significantly lower than severe ones—blood-cytokine levels (for example IL-1β, IL-1RA, IL-2R, IL-6, IL-7, IL-8, IL-9, IL-10, IFN-γ, TNF-α, G-CSF, GM-CSF, IP10, MCP1), can be increased." (PMID 34572585, 2021). "In AID patients with proven “mild” (stage I) COVID-19 the following therapies would be continued: immunoglobulin therapy (100%), HCQ (94.2%), IL-1 blockade with canakinumab and anakinra (72.5% and 79.2%, respectively) and IL-6 blockade (with support of 69.8% respondents)." (PMID 33683393, 2021). "Investigation of the level of IL-6 during the entire SARS-Cov-2 infection process could provide a comprehensive understanding of the dynamic changes in inflammation, which could be beneficial for the monitoring and treating patients with COVID-19." (PMID 33746945, 2021).
COVID-19 (continued). "This complement activation leads to enhanced production of endothelial-production of cytokines, such as IL-1, IL-8, RANTES, IL-6, and MCP-1, and up-regulates crucial endothelial adhesion molecules, such as P-selectin and VWF, which further helps to develop thrombin formation in COVID-19 patients." (PMID 33228225, 2020). "This hypothesis also reconciles the negative findings of studies evaluating IL-6 inhibitors with the uncontrolled evidence suggesting that IL-1 inhibition might be effective for COVID-19: indeed, IL-1 is found more upstream in inflammatory cascades than IL-6." (PMID 33442386, 2020). "Although IL-6 is regarded as a marker of pneumonia in CoV infections, it has now become evident that abrupt release of IL-1β and TNF-α could contribute to the severity of CoViD-19 pathogenesis." (PMID 32574269, 2020). "Without restimulation with PMA or incubation with monensin, a high percentage of GM-CSF+ and IL-6+ expressions could be found in CD4+ T-cells from COVID-19 patients in both ICU and non-ICU patients compared to healthy controls." (PMID 34676125, 2020). "Thus, targeting the IL-6 signaling pathway may reverse the hyperinflammation status and curb the CRS, potentially be the effective and safe way to reduce mortality of COVID-19." (PMID 33195318, 2020). "Moreover, IL-6 was found to be related to the exhaustion of CD4+ and CD8+ T cells in patients with COVID-19, evidenced by a negative association of IL-6 with the numbers of T lymphocytes." (PMID 33384605, 2020). "ICU patients with COVID-19 produced higher levels of IL-6 than those not requiring ICU care." (PMID 33269102, 2020). "The immune system is responsible for the resolution of COVID-19, however, overactivation of the immune system against SARS-CoV-2 can result in a severe cytokine storm due to the release of huge numbers of inflammatory factors such as IL-2, IL-6, IL-7, GM-CSF, IP10, MCP1, MIP1A, and TNF-α." (PMID 32781571, 2020). "In addition, COVID-19 patients with severe respiratory failure have macrophage activation syndrome or dysregulated immune responses, CD4 and natural killer cell cytopenia, and decreased HLA-DR expression in monocytes that can be due to an increase in IL-6." (PMID 33324210, 2020). "Second, some specific information regarding cardiovascular complications and inflammation such as echocardiography and interleukin-6 were not included in the study due to the limited conditions in the isolation ward and the urgency of constraining the COVID-19 epidemic." (PMID 33330541, 2020). "Despite the pulmonary injury, the production of pro-inflammatory cytokines including IL-1β, IL-6, TNF-α, macrophage inflammatory protein 1-α, interferon gamma-induced protein-10, and monocyte chemoattractant protein-1 were significantly enhanced in COVID-19 patients." (PMID 33041827, 2020). "Since expression of IL-6 has been considered a predictor of mortality, it also act as a pharmacological target, tocilizumab (TCZ) has already been studied in clinical trials in an effort to treat patients with severe COVID-19 by neutralizing these key inflammatory mediators." (PMID 32916821, 2020). "Interestingly, none of these 94 patients showed COVID-19 symptoms, which agrees with the reported efficacy of the IL-6 antagonists tocilizumab and sarilumab (unpublished observations) in COVID-19 treatment." (PMID 33519443, 2020). "High levels of He4 that significantly correlate with IL-6 and PSP have been detected in COVID-19 patients; for this reason He4 could be used as an innovative biomarker for monitoring the clinical evolution of the disease and for the pharmacological management of these patients." (PMID 33147871, 2020). "Thus, it is likely that, in severe cases of COVID-19, the development of DIC derives from multiple factors orchestrated by pro-inflammatory molecules, including IL-6, that concur in damaging blood vessels, interfering with coagulation, and inducing endothelial cell activation." (PMID 32655577, 2020).
COVID-19 (continued). "Notably, we observed that the classical monocytes and myeloid cells from severe COVID-19 patients in the single-cell RNA-seq data expressed high levels of S100A12, the gene encoding EN-RAGE, but not the typical inflammatory molecules IL-6 and TNF-α." (PMID 32788292, 2020). "To modulate, but not completely block, the activity of IL-6 may open a new path to treat severely ill COVID-19 patients by reduced complications." (PMID 32806722, 2020). "But, IL-6 was elevated in patients with COVID-19 irrespective of the presence of MetS." (PMID 33328246, 2020). "In addition, the IL-6:IL-10 and TNF-α:IL-10 ratios were significantly lower in COVID-19 patients as compared to non-COVID-19 patients (p = 0.0042 and p = 0.0001, respectively), driven by lower IL-6 and TNF-α levels in COVID-19 patients with similar levels of IL-10 between groups." (PMID 33272291, 2020). "The IL-6/IL-10 ratio may also be an important indicator for assessing the immune status of COVID-19 patients, although no established cutoff value is available to identify SIRS and/or MARS." (PMID 33240265, 2020). "Retrospective studies assessing the relationship between the prognosis of COVID-19 patients and levels of troponin I (TnI) and other cardiac injury biomarkers (creatine kinase [CK], CK myocardial band [CK-MB], lactate dehydrogenase [LDH], and interleukin-6 [IL-6]) were included." (PMID 32723362, 2020). "In COVID-19 tocilizumab may be considered in patients with high levels of inflammatory markers such as IL-6 and worsening respiratory insufficiency, requiring non-invasive ventilation or intubation." (PMID 33154972, 2020). "Given physiological roles of IL-6 in inflammatory conditions and the data from real world, IL-6 signal inhibitors, along with standard of care (SOC) treatment, might provide efficacy, offering the potential to treat COVID-19 in hospitalized populations more effectively than current SOC alone." (PMID 33024459, 2020). "Recent studies have shown elevated IL-6 levels in COVID-19 non-survivors compared to survivors." (PMID 32781571, 2020). "Studies have demonstrated that high level expression of inflammatory cytokines, such as IL-6, of IL-1β, interferon (IFN)-γ, interferon gamma-induced protein 10 (IP-10), TNF-α, and the chemokine, monocyte chemoattractant protein 1 (MCP-1) can correlate with the severity of COVID-19 symptoms." (PMID 33304309, 2020). "Thus, therapies targeting IL-6, IL-10, and TGF-β could be investigated as means of improving NK cell antiviral immunity in cases of COVID-19." (PMID 32973527, 2020). "By contrast, clinical trials of relevant IL-6, TNF, and JAK STAT inhibitors and blocking antibodies are applied to the adverse side of dysregulated IFN response, which are devised to mitigate the pathological IFN and pro-inflammatory response sustained in severe COVID-19." (PMID 33322160, 2020). "Transcriptomic analysis performed in samples from subjects with severe COVID-19 revealed the presence of low levels of type I and type III interferon genes together with elevated levels of proinflammatory cytokines and chemokines, such as IL-6, IL1RA, CCL2, CCL8 CXCL2, CXCL8, CXCL9, and CXCL16." (PMID 33159214, 2020). "Transcriptional profiling in normal human bronchial epithelial (NHBE) infected with SARS-CoV-2 shows upregulation of IL-6, suggesting that these lung epithelial cells may contribute to early IL-6 response seen in non-severe COVID-19 patients." (PMID 33335518, 2020). "Another popular candidate, Lianhuaqingwen (LH), was shown to significantly inhibit SARS-CoV-2 replication in Vero E6 cells and markedly reduce production of pro-inflammatory cytokines (TNF-α, IL-6, CCL-2/MCP-1 and CXCL-10/IP-10), suggesting that it might be a potential option for COVID-19 treatment." (PMID 33643033, 2020).